EZH2 (enhancer of zeste 2 polycomb repressive complex 2 subunit)
Diseases named in the same sentence as EZH2 in open-access papers (continued):
Sharing a sentence is not in itself a finding about the gene and the disease.
thyroid cancer (33 papers, 2017 to 2026). "In thyroid cancer, overexpression of EZH2 is linked to aggressive behavior and dedifferentiation in ATC and poorly differentiated thyroid cancer patients." (PMID 37175580, 2023). "Interestingly, expression levels of the ieGenes LPP in prostate adenocarcinoma and EZH2 in thyroid cancer have previously been associated with patient prognosis in cancer, and we observed a similar association within these two cancer types in the TCGA dataset." (PMID 35725412, 2022). "Overexpression of EZH2 has been identified in thyroid cancer, especially in ATC, and its inhibition results in antitumoral effects in vitro and in vivo, reducing cell growth, migration, and invasion and improving differentiation of ATC cells." (PMID 39876973, 2024). "For instance, LncRNA‐MIAT functions as a ceRNA to sponge miR‐150‐5p, boosting EZH2 expression and facilitating the thyroid cancer development." (PMID 38827027, 2024). "Nevertheless, further investigation is needed to determine the role of PRC2/EZH2 in thyroid cancer aggressiveness and dedifferentiation by implementing the use of gene-editing techniques, such as CRISPR/Cas9 in the ATC model." (PMID 37175580, 2023). "In thyroid cancer, EZH2 overexpression has been reported in ATC, and RNA interference modulation resulted in a reduction in cell migration and invasion in vitro in the 8505C cell line." (PMID 37175580, 2023). "Subsequently, EZH2 and E-cadherin expression levels were assessed in human thyroid cancers of different histotypes by qRT-PCR." (PMID 31963578, 2020). "LncRNA PVT1 modulates thyroid cancer cells’ proliferation by recruiting EZH2 and regulating thyroid-stimulating hormone receptor." (PMID 33126409, 2020). "EZH2 is one of the oncogenes upregulated in ATCs when compared to differentiated thyroid carcinomas." (PMID 33126409, 2020). "In a previous study, PVT1 was reported to promote the proliferation of thyroid carcinoma cells by recruiting EZH2 and mediating TSHR expression." (PMID 32596158, 2020). "It was notable that the enrichment of EZH2 was substantially higher, especially at the gene body region containing the +4919 CpG site in thyroid cancer compared to normal cells." (PMID 28416772, 2017). "PVT1 modulated thyroid cancer cell proliferation by recruiting EZH2 and regulating thyroid-stimulating hormone receptor." (PMID 29046366, 2017). "We first assessed EZH2 protein levels across a panel of thyroid cancer cell lines." (PMID 41147659, 2026). "Finally, our study showed that genes related to photodynamic therapy stress up, serum response dn, thyroid carcinoma anaplastic up, EZH2 targets up, and Nanog targets CGP were downregulated in the G15 condition." (PMID 41479593, 2025). "CCDC26 promotes thyroid cancer malignant progression via miR-422a/EZH2/Sirt6 axis." (PMID 36045445, 2022). "Upregulation of MIAT and EZH2 were positively related with LNM, high risk, recurrence and RAS mutation which indicates that MIAT and EZH2 may be played an important role in thyroid cancer progression." (PMID 34811354, 2021). "lncRNA PVT1 was reportedto modulate thyroid cancer cell proliferation by recruiting EZH2." (PMID 33650817, 2021). "Finally, we reported that PAR5 directly interacts with EZH2 in thyroid cancer cells, reducing its binding on the E-cadherin promoter, then relieving E-cadherin from the negative control by EZH2 in PAR5-overexpressing ATC cell lines." (PMID 31963578, 2020). "The authors finally proposed that PVT1 may contribute to pathogenesis of thyroid cancer through EZH2 recruitment and TSHR expression regulation." (PMID 32760219, 2020). "PAR5 interacts with EZH2 and reduces its protein level in thyroid cancer cells." (PMID 33126409, 2020). "Taken together, our findings suggested a potential role of EZH2 in thyroid carcinoma therapy." (PMID 31087496, 2019).
thyroid cancer (continued). "The result indicates that modulating EZH2 expression by miR‐124/506 mimics or EPZ‐6438 treatment may be a new strategy for the improvement of thyroid carcinoma therapy for the sorafenib insensitive patients." (PMID 31087496, 2019). "Therefore, we conclude that the suppression of EZH2 represents a potential target for thyroid carcinoma therapy." (PMID 31087496, 2019). "Finally, we revealed that EZH2, a subunit of polycomb repressor complex 2, dominant in thyroid cancer, might be responsible for regulating gene body methylation of METTL7A." (PMID 28416772, 2017). "The study showed that BANCR can be recruited by EZH2 to increase the expression level of thyroid-stimulating hormone receptor (TSHR) and promote the proliferation of IHH-4 thyroid cancer cells." (PMID 32596158, 2020). "In conclusion, our findings demonstrate that PAR5 downregulation was strictly related to the undifferentiated thyroid carcinomas and that PAR5 expression affected cell growth and migration rate by interacting with EZH2 and inhibiting its oncogenic activity." (PMID 31963578, 2020). "A study in thyroid cancer patients identified absent EZH2 expression in normal thyroid tissue and differentiated thyroid cancer, but presence in poorly differentiated (PDTC) and anaplastic thyroid cancers." (PMID 40075585, 2025). "Interestingly, mutual inhibition of EZH2 and HMGA, a group of architectural chromatin proteins that are overexpressed in thyroid cancer, significantly increased apoptotic rates and induced cell cycle arrest in ATC cells." (PMID 39876973, 2024). "To determine whether EZH2/PRC2 components are deregulated in PTC and ATC, we first analyzed the expression of EZH2, EED and SUZ12 in BRAFV600E thyroid cancer cell lines." (PMID 37175580, 2023). "Additionally, in thyroid cancer, MIAT contributes to tumor progression by absorbing miR-150-5p and modulate EZH2." (PMID 36941990, 2023). "The results suggested that compared with corresponding normal tissues, the methylation state of EZH2 was lower in BLCA, UCEC, LUAD, LUSC, prostate adenocarcinoma (PRAD), READ, testicular germ cell tumors (TGCT), and thyroid carcinoma (THCA), and higher in cholangiocarcinoma (CHOL)." (PMID 36545914, 2023). "Overall, we revealed that EZH2 interacted with the CpG site at the gene body of METTL7A and was responsible for MBD2 recruitment as well as RNA pol II rejection, which leads to METTL7A silencing in thyroid cancer." (PMID 28416772, 2017). "Consistently, EZH2 is overexpressed in ATC, but not in differentiated thyroid carcinomas." (PMID 31963578, 2020). "Moreover, it has been reported that PAR5 was able to directly bind EZH2 that, interestingly, was found overexpressed in ATC samples, but not in the differentiated thyroid carcinomas." (PMID 31963578, 2020).
head and neck squamous cell carcinoma (32 papers, 2012 to 2025). A squamous cell carcinoma that arises from any of the following anatomic sites: lip and oral cavity, nasal cavity, paranasal sinuses, pharynx, larynx, and salivary glands. "Therefore, the combination of EZH2-targeting with anti-PD-1 therapy may increase treatment susceptibility in head and neck squamous cell carcinoma (HNSCC)." (PMID 35300341, 2022). "In head and neck squamous cell carcinoma, Rap1GAP is repressed via EZH2, itself regulated by miR-101 and miR-26a, linking Rap1 to tumor invasion through a miR-101 → EZH2 → Rap1GAP → Rap1 axis." (PMID 40508181, 2025). "Further research identified EZH2 as a potential therapeutic target for encouraging antigen presentation and antitumor immunity in head and neck squamous cell carcinoma (HNSCC)." (PMID 36479105, 2022). "The study also found that tumor progression of an anti-PD-1-resistant head and neck squamous cell carcinoma (HNSCC) model can be suppressed by combinatorial treatment of an EZH2 inhibitor and anti-PD-1." (PMID 35003090, 2021). "EZH2 and H3K27me3 levels were significantly elevated in poorly differentiated head and neck squamous cell carcinoma (HNSCC), and inhibition of EZH2 could induce differentiation-related gene expression." (PMID 33011750, 2020). "Targeting and inhibition of EZH2 is a potentially effective therapeutic strategy for head and neck squamous cell carcinoma (HNSCC)." (PMID 30469511, 2018). "In numerous human cancers, including head and neck squamous cell carcinoma (HNSCC), EZH2 is frequently overexpressed or activated and has been identified as a negative prognostic factor." (PMID 38600608, 2024). "Zhou's team found that CRISPR-mediated inhibition of EZH2 was able to upregulate MHC class I expression and CD8 + T-cell proliferation in head and neck squamous cell carcinoma (HNSCC)." (PMID 39427211, 2024). "To discover novel strategies against head and neck squamous cell carcinoma (HNSCC), we performed genomics, metabolomics and RNA omics studies in HNSCC cells treated with EZH2 inhibitors." (PMID 33986254, 2021). "Three RBP genes (NOVA1, EZH2, and RBM24) were identified as central genes related to the prognosis of head and neck squamous cell carcinoma (HNSCC)." (PMID 33711033, 2021). "In the Squamous cell carcinoma of head and neck (HNSCC) data set of cancer genome map, the expression of EZH2 was negatively correlated with the pathway of antigen processing." (PMID 33344447, 2020). "A recent study revealed the inhibition of EZH2 could enhance cancer cell antigen presentation in head and neck squamous cell carcinoma (HNSCC) and avoid anti-PD-1 resistance." (PMID 32723346, 2020). "In chemoresistant Head and Neck Squamous Cell Carcinoma (HNSCC) cells, both the Wnt/β-catenin pathway and EZH2 are upregulated, indicating a relationship between higher EZH2 expression and Wnt/β-catenin pathway activation, contributing to chemoresistance and cancer stem cell accumulation." (PMID 39236081, 2024). "Among these miRNAs, miR-101 was the most frequently observed, since it has been described to target EZH2 in gastric cancer cell lines (BGC-823, SGC-7901, AGS, and MKN-45), in head and neck squamous cell carcinomas (HNSCCs) and in the glioblastoma cell line U87." (PMID 34991274, 2018). "EZH2, the catalytic component of the polycomb repressive complex 2 (PRC2), is responsible for H3K27me3 and has been shown to play a role in the development of prostate, breast, and head and neck squamous cell carcinomas." (PMID 28878842, 2017). "In the head and neck squamous cell carcinoma (SCC), EZH2 repressed Rap1GAP by facilitating the trimethylationof H3K27 and hypermethylation of the Rap1GAP promoter, and the downregulation of Rap1GAP activated the activity of Rap1, and eventually promoted proliferation and invasion." (PMID 28009991, 2017). "HINT2, the enhancer of zeste homolog 2 (EZH2) is overexpressed or activated in many human cancers including head and neck squamous cell carcinoma (HNSCC)." (PMID 30011966, 2018).
head and neck squamous cell carcinoma (continued). "In head and neck squamous cell carcinoma (HNSCC), a two-RBP gene signature (consisting of EZH2 and NOVA1) was constructed to predict the clinical prognosis of HNSCC patients, and this model will assist clinicians in providing a clinical diagnosis, individualized therapy, and prognostic assessment." (PMID 33461173, 2021). "Indeed, EZH2 did not regulate SNAI1 or SNAI2 gene expression in head and neck squamous cell carcinoma cell lines, and the inhibition of its expression repressed the expression of mesenchymal markers and inhibited migration and invasion capacities without modulating EMT-TF levels." (PMID 33291363, 2020). "EZH2 is a negative prognostic factor and is overexpressed or activated in most human cancers including head and neck squamous cell carcinoma (HNSCC)." (PMID 26378043, 2015). "However, it has been shown, in head and neck squamous cell carcinoma cell lines FaDu and SNU1041, that EZH2 did not regulate SNAI1 or SNAI2 gene expression." (PMID 34991274, 2018).
cholangiocarcinoma (31 papers, 2012 to 2025). A carcinoma that arises from the intrahepatic biliary tree (intrahepatic cholangiocarcinoma) or from the junction, or adjacent to the junction, of the right and left hepatic ducts (hilar cholangiocarcinoma). "This is in line with current concepts of EZH2 as a marker of “stemness” and indeed it is thought to be associated with de-differentiation in many malignancies, including cholangiocarcinoma (CCA), and is therefore, a common target of cancer therapy research." (PMID 27936185, 2016). "IL-6 secreted by vCAFs induces increased expression of EZH2 (enhancer of zeste homolog 2) in intrahepatic cholangiocarcinoma cells, driving epigenetic remodeling and thereby enhancing tumor aggressiveness." (PMID 41388158, 2025). "EZH2 was also reported to induce silencing of tumor-suppressive miRNA I tumor cells, and miR-34a was epigenetically silenced by EZH2, which promoted cholangiocarcinoma cell growth by activating the Notch pathway." (PMID 32206036, 2020). "Taken together, our results reveal that the effect of let-7c on invasion and distant metastasis capacities of cholangiocarcinoma cells is, at least partially, mediated by EZH2 and the DVL3/β-catenin axis." (PMID 29445149, 2018). "Taken together, the results demonstrate that EZH2 and DVL3/β-catenin are involved in the malignant behavior of cholangiocarcinoma, are associated with migration, invasion, distant metastasis, sphere formation, and tumor initiation and are regulated by let-7c." (PMID 29445149, 2018). "We also found that let-7c inhibits migration and invasion of cholangiocarcinoma cells, in vitro, by directly targeting the EZH2 protein." (PMID 29445149, 2018). "The miRNA let-7c thus plays an important dual role in regulating tumorigenic and metastatic abilities of human cholangiocarcinoma through mechanisms involving EZH2 protein and the DVL3/β-catenin axis." (PMID 29445149, 2018). "The results from the paired samples showed that both, EZH2 and β-catenin, were overexpressed in cholangiocarcinoma tissues." (PMID 29445149, 2018). "This dual role in regulating cholangiocarcinoma can be imitated by regulating EZH2 and DVL3 expression." (PMID 29445149, 2018). "EZH2 staining was positive in 96% of cholangiocarcinomas, including 3 highly differentiated Klatskin tumors." (PMID 22809481, 2012). "This dual role in the regulation of cholangiocarcinoma could be mimicked by the regulation of EZH2 and DVL3 expression." (PMID 35943151, 2022). "A previous study demonstrated that circ-CCAC1 elevated YY1 expression to promote cholangiocarcinoma (CCA) by sponging miR-514a-5p in CCA cells while elevating SH3GL2 expression to enhance cell permeability by directly sequestering EZH2 in the cytoplasm of human umbilical vein endothelial cells." (PMID 35045883, 2022). "Additionally, lncRNA DANCR upregulates FBP1 to accelerate proliferation and migration in cholangiocarcinoma via interacting with EZH2." (PMID 33292221, 2020). "In addition, SPRY4-IT1 exerted oncogenic properties via scaffolding EZH2/LSD1/DNMT1 in cholangiocarcinoma." (PMID 33029299, 2020). "To confirm whether EZH2 affects tumorigenesis capacity of cholangiocarcinoma, we transduced a lentivirus shRNA vector into TFK-1 cells in order to silence EZH2 and DVL3 genes and repeated the sphere formation and tumor-initiating assays." (PMID 29445149, 2018). "Twenty-three cholangiocarcinomas were also tested, and all but one proved to be positive for EZH2." (PMID 22809481, 2012). "In cholangiocarcinoma (CCA) cells, DANCR binds to EZH2 to facilitate histone methylation of the FBP1 promoter, ultimately suppressing FBP1 expression via epigenetic mechanisms." (PMID 38877534, 2024). "Similar epigenetic phenomena were described in human cholangiocarcinoma (CCA), in which Enhancer of zeste homolog 2 (EZH2)-mediated histone 3 trimethylation of lysine 27 (H3K27me3) in the same promoter lowered miR-34a levels and promoted Notch1 signalling." (PMID 37628760, 2023).
cholangiocarcinoma (continued). "In cholangiocarcinoma, rs887569 EZH2 SNP may serve as a possible predictive marker of overall survival in advanced CCA patients." (PMID 35813302, 2022). "Similarly, EZH2 expression was associated with vascular infiltration, the histological grades, and the cell proliferation activity in mixed hepatocellular cholangiocarcinoma (HCC-CCA)." (PMID 38275386, 2023). "After endothelial cells receive extracellular vesicles (mainly exosomes) carrying circ-CCAC1 released by cholangiocarcinoma cells, circ-CCAC1 can bind to EZH2 in endothelial cells and prevent the nuclear translocation of EZH2, weakening EZH2-mediated H3K27me3 modification of SG3GL2 promoter region." (PMID 33937077, 2021). "Upregulated SNHG1 could promote cholangiocarcinoma cell proliferation, migration, and cell cycle but reduce apoptosis, and the interaction between SNHG1 and EZH2 could target CDKN1A to promote the biological behavior of cholangiocarcinoma." (PMID 31691514, 2019). "We next determined whether EZH2 and DVL3/β-catenin affect migration and invasion in cholangiocarcinoma." (PMID 29445149, 2018). "In cholangiocarcinoma (CCA) cells (MZChA1, KBMC, and HuCCT1), the specific EZH2 miRNA, miR124, was also described to be decreased in tumors as compared with normal tissues." (PMID 31861179, 2019). "To further validate whether EZH2 and β-catenin were post-transcriptionally regulated by let-7c, we detected the expression of EZH2 and β-catenin proteins in tissues from cholangiocarcinoma patients and respective adjacent non-tumor tissues via western blot and immunohistochemistry." (PMID 29445149, 2018). "The result indicated that the mRNA expression of EZH2 and DVL3 was significantly increased in cholangiocarcinoma cells upon let-7c downregulation compared to the negative control group (P < 0.005 and 1.8125E−05, respectively)." (PMID 29445149, 2018).